TFAP2A (transcription factor AP-2 alpha)
Diseases named in the same sentence as TFAP2A in open-access papers (continued):
Sharing a sentence is not in itself a finding about the gene and the disease.
tumor (81 papers, 2000 to 2026). "Nowadays, studies have shown that TFAP2A plays essential roles in various tumor-associated biologic processes, including cell cycle, cell apoptosis, and Epithelial-mesenchymal transition (EMT)." (PMID 38265973, 2024). "We found that TFAP2A levels were significantly greater in tumour tissues than para-tumour tissues, and high expression of TFAP2A was associated with poor prognosis in NSCLC patients." (PMID 39695171, 2024). "In summary, these findings demonstrated that TFAP2A levels are elevated in tumour tissues compared to para-tumour tissues and are associated with poor prognosis of NSCLC patients." (PMID 39695171, 2024). "The clinical data revealed that a high level of TFAP2A was associated with increased tumour size, poor tumour differentiation, advanced TNM stage, and lymph node metastasis." (PMID 39695171, 2024). "For instance, in gastric adenocarcinoma, reduced TFAP2A expression was associated with advanced tumor stage and poor prognosis." (PMID 37291585, 2023). "In NSCLC, TFAP2A is implicated in promoting tumor-induced angiogenesis and inducing resistance to the anti-angiogenic effect of anlotinib via PDGFR, TGF-β, and VEGFR signaling pathways." (PMID 37291585, 2023). "In MM for example, gain in ATF1 and SOX10, associated with loss of TFAP2A expression, drive tumor growth and metastasis by regulating, in an opposing manner, a number of genes involved in cell adhesion, extracellular matrix remodeling, and cell survival." (PMID 35477713, 2022). "Three of them, ETS1, MYCN and TFAP2A, have been previously associated with the cancer progression and all of them show tumour promoting effects." (PMID 34198662, 2021). "The locus lies within a region containing TFAP2A, which encodes a transcriptional activation protein that interacts with several tumor suppressor genes." (PMID 23544012, 2013). "C6orf218, a gene encoding a hypothetical protein LOC221718, and a possible tumor suppressor gene, TFAP2A, are within 100 kb of rs9348512." (PMID 23544012, 2013). "TFAP2A was involved in regulating the function of tumor-associated macrophages in CRC." (PMID 40813717, 2025). "Importantly, the tumor-suppressive actions mediated by the miR-8072/TFAP2A axis were intricately associated with the attenuation of AKT/ERK signaling cascades and the blockade of EMT processes." (PMID 38890750, 2024). "In addition, UMUC3-associated tumor xenograft volume was significantly increased following overexpression of TFAP2A (p < 0.05; quantified in 8k) and TFAP2C (p < 0.01; quantified in 8l)." (PMID 31772149, 2019). "Our study reveals that in NSCLC cells, upregulated PRMT3 promotes IDO1 expression by methylating TFAP2A, thereby activating the tumor’s intrinsic Kyn metabolism and mediating the development of radiation resistance." (PMID 41129671, 2026). "Tfap2aΔHep and Tfap2aΔMΦ mice treated with DEN/CCl4 for 6 months increased tumor burden compared to Tfap2a flox controls." (PMID 40180937, 2025). "The results showed that the TFAP2A-knockdown group exhibited lower tumor burden and reduced liver metastasis incidence when combined with gemcitabine, compared to controls." (PMID 40727938, 2025). "We propose that HPV oncoproteins E6 and E7 cooperate with these master TFs (TP63, AP-1, and TFAP2A) to nucleate tumor-specific super-enhancer clusters in HPV+ HNSCC." (PMID 41323280, 2025). "The present study demonstrated that TFAP2A overexpression promoted tumour proliferation, invasion, and migration." (PMID 39695171, 2024). "Overall, the functional mechanism of TFAP2A in cancer appears to be complex and context-dependent, with oncogenic and tumor-suppressive functions depending on the specific cancer type, interaction molecular and cellular context." (PMID 38265973, 2024). "The present study demonstrated that TFAP2A was highly expressed in different tumours, including LUAD and LUSC, according to the TIMER2.0 database." (PMID 39695171, 2024).
tumor (continued). "The colony formation assay showed that the proliferation of TFAP2A-overexpressing and control tumour cells decreased when ESR2 was knocked down." (PMID 39695171, 2024). "Similar to its expression abundances in tumor tissues, TFAP2A mRNA expression also showed low tissue specificity." (PMID 38265973, 2024). "We discovered that the expression of TFAP2A was significantly associated with the expression of immune checkpoint genes, immune subtypes, ESTIMATE scores, tumor-infiltrating immune cells, and the possible role of TFAP2A in predicting immunotherapy efficacy." (PMID 38265973, 2024). "A subcutaneous tumour model in nude mice was constructed to further verify the oncogenic role of TFAP2A." (PMID 39695171, 2024). "TFAP2A has been suggested to function as a tumor suppressor in many cancers, but recently, many studies reported the tumor-promoting effects of TFAP2A in different cancer types." (PMID 38890750, 2024). "The subcutaneous tumours were analysed by IHC, which demonstrated that the expression levels of TFAP2A, ESR2 and Ki67 were decreased in tumours derived from TFAP2A-knockdown cells but increased in tumours derived from TFAP2A-overexpressing cells." (PMID 39695171, 2024). "Building upon our previous findings regarding the anti-tumor effects of miR-8072, we conducted further investigations to validate the involvement of TFAP2A in TNBC." (PMID 38890750, 2024). "In vitro and in vivo experiments confirmed that the expression of the TFAP2A gene in CC is higher than that in normal people and is related to the tumour stage and local metastasis." (PMID 39735605, 2024). "Colony formation assays of A549 and H1703 cells showed that TFAP2A overexpression promoted the growth of tumour cells and that TFAP2A knockdown inhibited tumour cell growth." (PMID 39695171, 2024). "In contrast to TFAP2C, extensive research indicates that TFAP2A plays a significant tumor suppressive role in breast tissues, exhibiting functions crucial for growth suppression and maintenance of the differentiated state." (PMID 38890750, 2024). "The protein level of TFAP2A was positively related to tumour diameter, tumour differentiation, TNM stage, and lymph node metastasis." (PMID 39695171, 2024). "qRT‒PCR analysis of 102 paired tumour and para-tumour tissues indicated that the mRNA level of TFAP2A was significantly elevated in tumour tissues, and the TFAP2A level was twofold greater in 80% of paired tissues." (PMID 39695171, 2024). "The result showed immune-related TDGF1 was positively modulated by TFAP2A and reminded us of the function of TFAP2A in tumor immunity." (PMID 38265973, 2024). "By integrating the results, we found the potential common roles of TFAP2A in pan-cancer were related to tumor immunity." (PMID 38265973, 2024). "Members of the transcription factor activator protein-2 (TFAP-2) family (TFAP2A, TFAP2B, TFAP2C, TFAP2D and TFAP2E) are associated with various pathophysiological processes, including tumours." (PMID 39695171, 2024). "The protein levels of TFAP2A were elevated in three tumor tissue samples compared to the adjacent normal tissues." (PMID 38265973, 2024). "The function of TFAP2A in prognosis and tumor immunity in pan-cancer was still controversial and obscure." (PMID 38265973, 2024). "According to the findings, TFAP2A expression was up-regulated in tumor tissue and negatively correlated with CRTAC1 expression (r = − 0.184, p < 0.001)." (PMID 38755183, 2024). "The binding of TFAP2A to the PD-L1 promoter region is beneficial for its high expression, thereby forming a positive feedback loop during tumour growth." (PMID 39735605, 2024). "WW Domain Containing Oxidoreductase (WWOX) protein acts as a tumor suppressor by interacting with TFAP2A and 2C." (PMID 37291585, 2023). "Similar results were obtained in CT26 mouse models, Tfap2a slowed tumor progression and decreased Pdl1 expression accompanied by increased Cd8+ T cells and effector molecules in CT26 tumor tissues." (PMID 37330579, 2023).
tumor (continued). "In recent years, studies on TFAP2C have found that it has similar DNA binding sites, similar anti-tumor effects and mechanisms with TFAP2A." (PMID 37859819, 2023). "As expected, Tfap2a combined with anti-PD-1 antibodies to improve Cd8+ T cell infiltration and inhibit tumor progression." (PMID 37330579, 2023). "As the results indicated, the expressions of CDCA3, MYCN and TFAP2A in ccRCC tumor tissue were significantly upregulated compared with those in adjacent normal kidney tissue, while the expressions of ACADSB and CHAC1 were significantly downregulated." (PMID 37064095, 2023). "Mechanistically, TFAP2A directly binds to the CD133 promoter to ignite tumor stem-like properties in HCC cells and synergizes with periostin/TGFβ1 positive feedback loop to further boost tumor stemness." (PMID 37291585, 2023). "Although TFAP2A has been described to be a tumor suppressor in some cancer types, it can also act as an oncogenic factor to promote cancer cell proliferation and metastasis." (PMID 36707053, 2023). "Transcriptional factor TFAP2A controlled the expression of various tumor-related genes including VEGF, BCL-2, c-Kit and c-Myc, and was reported to be widely upregulated in tumor samples." (PMID 37064095, 2023). "In NSCLC, both TFAP2A and TFAP2B are implicated in promoting tumor-induced angiogenesis via platelet-derived growth factor receptor (PDGFR), vascular endothelial growth factor receptor (VEGFR) and TGF-β signaling pathways." (PMID 37291585, 2023). "It has been shown that TFAP2A regulates tumor growth, metastasis, and cancer progression by interacting with noncoding lncRNAs and miRNAs." (PMID 36707053, 2023). "Posttranslational modifications also influence the tumor-promoting and tumor-suppressing functions of TFAP2A and TFAP2C during the EMT process." (PMID 37291585, 2023). "We have previously shown that normal urothelial cells transformed by As3+ form tumors which show strong staining for TRIM29, TFAP2A and P63 in the undifferentiated part of the tumor and weak staining in the areas of squamous differentiation." (PMID 36293167, 2022). "MiR-3960 antagonizes the promotion effect of tumor-derived exosomes on the proliferation, invasion, and metastasis of PC via suppressing TFAP2A." (PMID 36284637, 2022). "For the first time, we demonstrated that miR-3960 in exosomes of PC inhibits tumor proliferation, metastasis, and invasion via TFAP2A." (PMID 36284637, 2022). "In comparison to the si-NC group, the lung and liver morphology in the si-TFAP2A group were normal and complete, and the tumor metastases were less." (PMID 36284637, 2022). "According to TFAP2A expression of tumor tissues, we divided patients of TCGA-LUAD dataset into three groups: high, middle and low group." (PMID 33824285, 2021). "We found that, compared with normal tissues, the TFAP2A mRNA levels in tumor tissues were all significantly increased." (PMID 33824285, 2021). "By immunohistochemistry scoring (127 contact pairs eventually retaining), we found protein expression of TFAP2A in tumor tissues was also up-regulated, mainly distributed in the nucleus, and statistically significant." (PMID 33824285, 2021). "It has been shown that the interplay of WWOX and TFAP2A/TFAP2C affects the biology of the tumor thus corresponding bioinformatics analyses involving BLCA cohort were performed as a follow-up of in vitro experiments." (PMID 33691672, 2021). "Herein, we demonstrated that in multiple independent datasets, TFAP2A exhibited high expression in LUAD and elevated TFAP2A levels strongly indicated poorer prognosis, heralding tumor-promoting function of TFAP2A in LUAD." (PMID 33824285, 2021). "Resistant tumor cells highly expressed LINC00160 to recruit transcriptional factor TFAP2A, which bound to SAA1 promoter regions and activated its expression." (PMID 32921632, 2020).
tumor (continued). "ITPKA contributes to tumor proliferation, migration and cell death in-vitro, moreover, we provide evidence that TFAP2A transcriptionally induce the hyper-expression of ITPKA." (PMID 32015686, 2020). "The tumor-suppressive function of ZNF471 was mediated by directly inhibiting its downstream targets TFAP2A and PLS3 transcription." (PMID 29610526, 2018). "We analyzed the expression of TFAP2A in 57 paired tumor and normal samples from patients with NSCLC in The Cancer Genome Atlas (TCGA) database, and found that TFAP2A was significantly induced in tumor samples, consistently with HO-1." (PMID 28749936, 2017). "TFAP2A and MZF1 have both been implicated in the regulation of genes that control tumour invasiveness and metastases and the pathological process of EMT is known to underpin many cancer types with evidence supporting its role in metastatic cancer cells." (PMID 26697505, 2016). "The transcription factor AP-2α (TFAP2A), a RA-inducible gene with tumor-suppressing activity, was upregulated by CRABP1 depletion and RA treatment at a dose up to 5 nM." (PMID 26142905, 2015). "TFAP2A is a well-recognized tumor suppressor in many tumor types via its activation of p21 Waf1/Cip1 expression, which leads to cell cycle arrest (reviewed in 23)." (PMID 24023917, 2013). "Since AP-2α (TFAP2A) is often downregulated in human cancers and acts as a tumor-suppressor gene, the further efforts were especially made in understanding how AP-2α is regulated by Aurora-A." (PMID 21829699, 2011). "TFAP2A has been shown to act as a tumor suppressor gene and plays an important role in cancer cell chemosensitivity." (PMID 20184741, 2010). "In fact, many reports demonstrated that TFAP2A plays a major role in development and we recently showed a function for TFAP2A in cell migration and/or invasion for tumor cells and neurons." (PMID 20525283, 2010). "TFAP2A was shown to be highly expressed in ductal tumor cells while normal cells expressed TFAP2A in the inner glandular cell layer." (PMID 19116033, 2008). "Thirteen primary tumours were further analysed using microsatellite markers D6S470 and D6S263 for loss of heterozygosity (LOH) of a locus harbouring TFAP2A." (PMID 10864211, 2000). "Application of these state-of-the-art tools to NSCLC models could further clarify the dynamic regulation of CES3 and TFAP2A in the tumor microenvironment and identify biomarkers predictive of response to metabolism-targeted therapies." (PMID 41438579, 2026). "AOC1 and TFAP2A levels were increased in NSCLC tumor tissues and cell lines (A-549 and NCI-H1299)." (PMID 40813717, 2025). "In ER-positive breast cancer, a few studies have shown that TFAP2A promotes tumor progression." (PMID 38890750, 2024). "However, TFAP2A is also a tumour suppressor; for example, it is underexpressed in hepatocellular carcinoma." (PMID 39735605, 2024). "Furthermore, our findings indicate that the downregulation of TFAP2A plays a crucial role in mediating the tumor-suppressive effects of miR-8072 by inhibiting the EMT process and AKT/ERK signaling pathways." (PMID 38890750, 2024). "We first determined the expression of TFAP2A in normal and tumor tissues." (PMID 38265973, 2024). "The result shows that TFAP2A overexpression promoted the resistance of tumour cells to osimertinib." (PMID 39695171, 2024). "TFAP2A knockdown decreased the tumour size and inhibited tumour growth." (PMID 39695171, 2024). "In tumor models, both TFAP2A and TFAP2C are important to cell proliferation and migration." (PMID 38890750, 2024). "Based on these results, the oestrogen signalling pathway may play an important role in the promotion of tumour progression by TFAP2A." (PMID 39695171, 2024). "Interestingly, TFAP2A has been shown to have dual roles in other species, acting as both a tumor suppressor and an oncogene depending on the cellular context." (PMID 39769404, 2024). "Previous studies based on public databases have shown that TFAP2A is highly expressed in tumours." (PMID 39695171, 2024).
tumor (continued). "To further clarify whether TFAP2A expression had influences on tumor immunity, we studied the effect of TFAP2A interference on PD-L1 expression using two cancer cell lines." (PMID 38265973, 2024). "The Tfap2a-induced tumor regression was attenuated by Cd8 neutralization." (PMID 37330579, 2023). "Tfap2a could decrease Pdl1 expression in tumor cells, increase the infiltration of Cd8+ T cells, enhance effector molecule release, and suppress tumor growth in vivo." (PMID 37330579, 2023). "WWOX/TFAP2A demonstrates anti-tumor functions, while WWOX/TFAP2C still promotes oncogenesis." (PMID 37291585, 2023). "TFAP2A functions as a tumor suppressor and influences response to therapy in several cancer types." (PMID 37859819, 2023). "The results of analyzing the TFAP2A gene showed that the gene expression was negatively correlated to LUAD tumor purity, which means that the cells of the neoplastic microenvironment are characterized by a slightly higher expression of this gene in relation to the LUAD cells (p = 0.0456)." (PMID 36831334, 2023). "We silenced TFAP2A in vivo to observe the tumor proliferation and invasion." (PMID 36284637, 2022). "Furthermore, the effects of exosomes and the miR-3960/TFAP2A axis on PC tumor growth were observed in tumor-bearing mice by the measurement of tumor weight and volume, and hematoxylin-eosin staining." (PMID 36284637, 2022). "Indeed, the association between increased TFAP2A and TFAP2C expression was observed in both the TCGA BC cohort, as well as our in-house tumor cohort." (PMID 31772149, 2019). "Finally, cluster 4 is distinguished by a low point mutation burden (~80 coding mutations per tumor), as well as high expression of three genes (BTBD9, CDYL, TFAP2A) and high methylation at 100 promoters." (PMID 30367051, 2018). "Collectively, these results suggested that the tumor-suppressive effects of ZNF471 on cell proliferation, migration, and invasion are associated with the transcriptional suppression of its downstream target TFAP2A and PLS3." (PMID 29610526, 2018). "Since TFAP2A (encode AP-2α) could be directly targeted by miR-200b, decreased miR-200b enhanced AP-2α/ TGF-β signals in CCA for tumor metastasis." (PMID 29084594, 2017). "For instance, TFAP2A can regulate tumor cell migration and apoptosis." (PMID 28684851, 2017). "Using linear regression we found four DNA methylation markers, MT2, SFRP2, TFAP2A, and TWIST1, that showed individual association with tumor subtype at p<0.05 significance level, however, after adjusting for multiple comparisons, none of these associations remained statistically significant." (PMID 22028801, 2011). "However in HeLa cells, used for our microarray analysis, we demonstrated that TFAP2A regulates tumor cell motility and invasion, at least partially, via DCBLD2/ESDN in a negative manner." (PMID 20525283, 2010). "Furthermore, the overexpression of both TFAP2A and ESR2 in NSCLC cells was associated with the overactivation of MAPK signalling, and the combination of PHTPP and osimertinib had a synergistic effect on suppressing tumour growth." (PMID 39695171, 2024). "Thus, TFAP2A plays an important role in the development of tumours." (PMID 39695171, 2024). "In addition, the TFAP2A level was positively related to important proliferative markers (Ki67, PCNA and HDNC1), which suggested that TFAP2A may promote the proliferation of tumours." (PMID 39695171, 2024). "Moreover, Tfap2a can enhance anti-tumor immunity and the efficacy of anti-PD-1 therapy." (PMID 37330579, 2023). "Furthermore, as a transcription factor, TFAP2A has a wide range of substrates, thus playing different roles in distinct pathways, which might be either oncogenic or tumor suppressive potential." (PMID 33824285, 2021).